ABCA1 (ATP binding cassette subfamily A member 1)
Diseases named in the same sentence as ABCA1 in open-access papers (continued):
Sharing a sentence is not in itself a finding about the gene and the disease.
amyloid (13 papers, 2012 to 2025). "In this study, we demonstrate for the first time that the deletion of mir‐33 in an amyloidosis mouse model significantly increases ABCA1 protein levels, increases apoE lipidation, and reduces the levels of insoluble Aβ peptides and amyloid plaque deposition." (PMID 39345217, 2024). "We demonstrated that deletion of mir‐33 significantly increased ABCA1 protein levels, increased the lipidation of apoE, and reduced amyloid pathology and gliosis at 8 months of age." (PMID 39345217, 2024). "Our results suggest that exosomal transport of ABCA1/miR‐384 from the neurons to CSF and peripheral blood contributes to abnormal amyloid deposition in the brain and subsequent development of AD." (PMID 35470961, 2022). "Treatment of AD mice with synthetic LXR agonists, including TO901317 and GW3965, consistently improves cognitive performance and can decrease amyloid burden, and we have shown that ABCA1 is required for the beneficial effects of GW3965 in AD mice." (PMID 27598782, 2016). "Therefore, miR‐33 is a potential target for modulating ABCA1 protein levels and ameliorating amyloid pathology." (PMID 39345217, 2024). "Interestingly, several studies have shown that knocking out Abca1 in amyloidosis mouse models increases the formation of Aβ peptides and amyloid plaque deposition." (PMID 39345217, 2024). "Although the significance of ABCA1 overexpression in amyloid pathology has been demonstrated in a mouse model, there was a lack of human data linking ABCA1 to an increased risk of developing AD." (PMID 39345217, 2024). "Thus, it is a promising approach to identify therapeutic targets to increase ABCA1 expression and reduce amyloid pathology." (PMID 39345217, 2024). "This study investigated whether microRNA‐33 (miR‐33)‐mediated regulation of this ABCA1–APOE pathway affects phenotypes of an amyloid mouse model." (PMID 39345217, 2024). "Reduced amyloid deposition and improved Aβ clearance have been observed in an AD mouse model after overexpressing ABCA1 transporter, whereas deletion of the ABCA1 gene decreases levels of apoE protein and increases the deposition of Aβ." (PMID 32882843, 2020). "Additionally, inducing Abca1 using either pharmacological or genetic methods can improve cognitive function and reduce amyloid levels in AD mouse models and increase apoE lipidation in the brain." (PMID 27598782, 2016). "The data suggests that the LXR agonist GW3965 is associated with increased expression of ApoE and ABCA1 in the hippocampus and cerebral cortex without a detectable reduction of the amyloid load." (PMID 26720273, 2015). "Further, loss of a single copy of Abca1 leads to cognitive deficits and increased amyloid burden in APOE4- but not in APOE3-expressing AD mice, suggesting that apoE4 functions may be particularly sensitive to its lipidation status." (PMID 27598782, 2016). "Despite modest impacts on amyloid pathology, bexarotene did indeed engage the LXR target gene Abca1, resulting in elevated mRNA and protein levels in the brain (top and bottom)." (PMID 29448961, 2018). "SAA receptors, such as SELS (glucose homeostasis and ER stress), ABCA1, ABCA7, SCARB1 (cholesterol efflux), CD36, TLR2, TLR4, CST3 (inflammatory signaling), FPR2 (chemotaxis and immune cell activation), and AGER (amyloidosis), have been reported previously." (PMID 27799725, 2016). "Nuclear receptor agonists upregulate ABCA1, ABCG1, and APOE gene expression, which increases apoE lipidation, facilitates Aβ clearance, reduces amyloid pathology, and reverses memory deficits in an amyloid mouse model." (PMID 32882843, 2020).
colon cancer (13 papers, 2013 to 2025). "Smith and Land demonstrated in colon cancer cells that ABCA1 had an anticancer activity in which deficiency allowed for increased mitochondrial cholesterol, inhibited release of mitochondrial cell death-promoting molecules, and facilitated cancer cell survival." (PMID 23762832, 2013). "Three of the eight colonic tumor-related genes, ABCA1, PLA2G7, and SCARB1, were significantly correlated with GLS, the main enzyme for glutamate metabolism." (PMID 36843944, 2023). "For example, Smith and Land demonstrated that overexpression of ABCA1 in colon cancer cells resulted in a decrease of cellular cholesterol and inhibition of tumor growth in vitro and in vivo." (PMID 25628764, 2015). "ABCA1 was previously revealed to have antitumor effects and expresses in low level in colon cancer." (PMID 38827789, 2024). "Thus, in contrast to previously cited findings, ABCA1 is proposed as a potential colon cancer suppressor, while miR-183 is proposed as an oncogene." (PMID 33805921, 2021). "ABCA1 is also aberrantly expressed in colon cancer tissues and cells." (PMID 32194787, 2020). "However the activation of PPARγ can lead to increased ABCA1 gene transcription in macrophages and ABCA1 has shown to have anticancer activity in colon cancer cells." (PMID 32982759, 2020). "Silencing ABCA1 or miR-183 promoted proliferation and inhibited apoptosis in colon cancer cells." (PMID 32194787, 2020). "The combined analysis of these 4 genes, ABCA1, ACSL1, AGPAT1 and SCD, constitutes a metabolic-signature (ColoLipidGene) able to accurately stratify stage II colon cancer patients with 5-fold higher risk of relapse with strong statistical power in the four independent groups of patients." (PMID 25749516, 2015). "Apabetalone has recently been shown to inhibit ABCA1 protein expression in Caco-2 colon cancer cells and inhibit tumor promoting behavior including proliferation, migration, invasion and reverse the EMT phenotype observed in ABCA1 overexpressing Caco-2 cells." (PMID 35582032, 2021). "The model including the four LMGs (ABCA1, ACSL1, AGPAT1 and SCD) is proposed as a prognostic marker of colon cancer with stage II, but not effective in all stages of colon cancer." (PMID 37055842, 2023).
glioma (13 papers, 2013 to 2025). A benign or malignant brain and spinal cord tumor that arises from glial cells (astrocytes, oligodendrocytes, ependymal cells). "The survival plots reveal lower expression levels of ABCA1 associated with better OS for glioma patients." (PMID 37749600, 2023). "Meanwhile, ROC analysis indicates that ABCA1 shows an exceptional diagnostic value and performance in distinguishing glioma tissues from normal brain tissues with the numerical value of AUC up to 0.957 (95% CI 0.861–0.923)." (PMID 37749600, 2023). "We explored the ABCA1 associated clinical outcomes for glioma patients through several web databases and bioinformatics tools." (PMID 37749600, 2023). "Subsequently, we evaluated the diagnostic performance of ABCA1 in distinguishing glioma tissues from normal brain tissues through the ROC curve." (PMID 37749600, 2023). "The diagram exhibits that ABCA1 expression remarkably negatively associates with TMZ resistance in central nervous system tumors, especially in diffuse glioma (Pearson r = − 0.41, p = 0.038) and astrocytoma (Pearson r = − 0.55, p = 0.0043)." (PMID 37749600, 2023). "Therefore, the result that ABCA1 is positively associated with IL-10 confirms the positive correlation of ABCA1 with M2 macrophage infiltration in glioma." (PMID 37749600, 2023). "Astrocyte‐derived cholesterol is key to glioma cell survival, and that targeting astrocytic cholesterol efflux, via ABCA1, halts tumour progression." (PMID 40917390, 2025). "All the results revealed that a mounting infiltration abundance of M2 macrophages in glioma was primarily related to the highly expressed level of ABCA1." (PMID 37749600, 2023). "The analysis results based on 681 glioma tissues and 207 normal tissues from the GEPIA2 database display higher ABCA1 expression levels in glioma than in normal tissues." (PMID 37749600, 2023). "Among the patients with glioma, the survival prognosis in high-expression groups of ABCA1 is prominently inferior to that in low-expression groups." (PMID 37749600, 2023). "The result demonstrates that the higher the level of ABCA1 expressed in glioma cells, the lower the activity of TMZ." (PMID 37749600, 2023). "An upregulated drug metabolism-related protein, efflux transporter protein ABCA1, was discovered in glioma datasets." (PMID 37749600, 2023). "The mRNA expression data measured by real-time PCR revealed that the expression level of ABCA1 in TMZ-resistant glioma cells (U118-R and T98G-R) was significantly higher than that in non-resistant glioma cells (U118 and T98G)." (PMID 37749600, 2023). "Based on the markers of immune cells, we finally found an abundance of M2 macrophages infiltrating in glioma tissues with high levels of ABCA1." (PMID 37749600, 2023). "The result displays that glioma patients with higher ABCA1 expression levels have encountered worse OS, DSS, and PFI." (PMID 37749600, 2023). "We thereupon explored the correlation between ABCA1 and tumor-immune infiltration cells in glioma from multiple levels." (PMID 37749600, 2023). "Our findings indicate that ABCA1 knockdown or inhibition is a potential strategy for improving the therapeutic efficacy of gliomas." (PMID 37749600, 2023). "The LinkedOmics database was adopted for gene correlation and enrichment analysis of the TCGA glioma to investigate the biological roles of ABCA1 in glioma." (PMID 37749600, 2023). "The immunohistochemical staining of ABCA1 shows intense staining in glioma tissues and weak in normal tissues, which reveals the highly expressed level of ABCA1 in glioma patients." (PMID 37749600, 2023). "High expression levels of ABCA1 indicate poor prognosis in glioma patients and unsatisfied chemosensitivity of TMZ." (PMID 37749600, 2023). "The numerical value of AUC (0.957, 95% CI 0.861–0.923) indicates that ABCA1 has a superb capability in glioma diagnosis." (PMID 37749600, 2023). "A raised death rate of glioma stem-like cells was discovered after using ABCA1 antagonists followed by TMZ treatment." (PMID 37749600, 2023).
glioma (continued). "The significantly over-expressed mRNA and protein levels of ABCA1 exist in glioma tissues compared to normal brain tissues." (PMID 37749600, 2023). "One efflux transporter, ATP-binding cassette transporter subfamily A1 (ABCA1), was discovered with an upregulated expression level and signaled poor clinical outcomes for glioma patients." (PMID 37749600, 2023). "The data of colony formation analysis and CCK-8 showed ABCA1 knockdown significantly reduced proliferation and colony formation ability of glioma cells." (PMID 37749600, 2023). "According to the analysis of ABCA1 expression data in three GEO datasets and the TCGA database, we discovered that the expression level of ABCA1 in glioma was significantly elevated in comparison to the normal brain tissues." (PMID 37749600, 2023). "Higher expression levels of ABCA1 in glioma tissues were discovered than in normal brain tissues and indicated poor prognosis in patients with glioma." (PMID 37749600, 2023). "The GEO dataset of glioma showed that the ABCA1 level was higher in GBM tissues than in normal brain tissues." (PMID 33436575, 2021). "In the glioma tumor initiating cells, LXRβ activated transcription of ABCA1, but also immune modulation pathways and the production of glycerophospholipids." (PMID 31664073, 2019). "To determine which LXR paralog was likely to be activating ABCA1 in our glioma cells, we used the UCSC Xena browser to look at expression levels of NR1H2 and NR1H3 in normal tissues in the Genotype-Tissue Expression (GTEx) data set." (PMID 31664073, 2019). "Glioma cells with CRISPR-modified NR1H2 (crLXRβ-1) expressed less ABCA1 in membrane fractions of cells at high cell density than cells modified by a non-targeting CRISPR control (crNT)." (PMID 31664073, 2019). "We confirmed this result with quantitative real time PCR, plating glioma cells at low (sparse) or high (dense) density and measuring ABCA1 RNA expression levels 24, 48, or 72 hrs after plating." (PMID 31664073, 2019). "This supports the notion that oxysterol synthesis provides an autocrine signal that enhances ABCA1 expression thereby increasing S1P export from glioma cells." (PMID 26002572, 2015). "The present in vitro data suggest that interference with de novo SL synthesis, signaling via S1P receptors, or efflux of S1P (ABCA1) attenuates U87MG glioma cell proliferation." (PMID 26002572, 2015). "Glyburide-mediated inhibition of ABCA1 resulted in intracellular accumulation of S1P raising the possibility that ABCA1 promotes S1P efflux in U87MG glioma cells thereby contributing to inside-out signaling." (PMID 26002572, 2015). "An additional member, ABCA1, was investigated as its elevation after irradiation has been reported in glioma." (PMID 24219920, 2013). "After confirming the LXR‐loaded nanodiscs are able to increase expression of the ABCA1 cholesterol efflux transporter, we compared the effectiveness of each treatment with regards to cholesterol removal from glioma cells, as this is expected to be one of the main drivers of tumor cell death in vivo." (PMID 40249282, 2025). "Overexpressed ABCA1 stimulates the infiltration of macrophages (M2) in glioma." (PMID 37749600, 2023). "The role of ABCA1 in the progression and prognosis of glioma also remains a notable question." (PMID 37749600, 2023). "Treatment with TMZ after ABCA1 knockdown enhances the chemosensitivity, suggesting that inhibition of ABCA1 may be a potential strategy for improving the therapeutic efficacy of gliomas." (PMID 37749600, 2023). "Additionally, data from the UALCAN database indicate that ABCA1 is over-expressed in glioma samples at the level of mRNA and protein." (PMID 37749600, 2023).
glioma (continued). "The CellMinerCDB platform conducted a correlativity analysis of ABCA1 expression and TMZ activity in glioma cell lines to investigate whether ABCA1 augmented TMZ resistance in the treatment of glioma patients." (PMID 37749600, 2023). "Accordingly, ABCA1 may also promote chemoresistance of glioma through the mechanism of efflux of TMZ, and its role is worthy of further investigation." (PMID 37749600, 2023). "Additionally, co-expression and immunological analysis revealed that ABCA1 facilitates the immune infiltration of M2 macrophages in glioma, thereby stimulating tumor growth and aggravating the poor survival of patients." (PMID 37749600, 2023). "Additionally, the results of co-expression and immunological analysis demonstrated that ABCA1 participated in the immune regulation and immune cell infiltrating (especially M2 macrophages) in glioma." (PMID 37749600, 2023). "Interestingly, the present study, for the first time, demonstrated a significant positive correlation of LRP-1 with ABCA-1 in glioma tumor samples as well as in the external data sets." (PMID 36267880, 2022). "We next determined whether LXR turns on the expression of ABCA1 in our glioma tumor neurosphere cells." (PMID 31664073, 2019). "Overall, our data indicate that ABCA1 plays a crucial role in regulating efflux of cholesterol in highly dense glioma cells, but LXRβ signaling maintains safe levels of cholesterol through a more complicated balance of biosynthesis, uptake, and efflux of cholesterol." (PMID 31664073, 2019). "Our findings indicate that de novo SL synthesis, S1P receptor-mediated signaling, and ABCA1-mediated S1P efflux could provide pharmacological targets to interfere with glioma cell proliferation." (PMID 26002572, 2015). "Moreover, ABCA1 in glioma may facilitate the immune infiltration of M2 macrophages which promote tumorigenesis and predict poor clinical outcomes for patients." (PMID 37749600, 2023). "It revealed that ABCA1 expression had a positive correlation with the abundance of T helper cells, T gamma delta, macrophages, T effector memory cells, T central memory cells, neutrophils, activated dendritic cells (aDC), eosinophils and Th17 cells in glioma (p < 0.05)." (PMID 37749600, 2023). "By upregulation of ATP‐binding cassette transporter A1 (ABCA1), LXR agonists synergize with sHDL nanodiscs to deplete cholesterol and induce apoptosis of glioma cells." (PMID 40249282, 2025). "Subsequent testing of each formulation in glioma cells demonstrated effective delivery of LXR agonists and upregulation of one of the key downstream targets of LXR activation, ABCA1." (PMID 40249282, 2025). "Our study discovered an overexpressed level of ABCA1 in the glioma tissues and TMZ-resistant cells deriving from glioma." (PMID 37749600, 2023). "According to the mentioned findings, we conducted a correlation analysis between ABCA1 expression and the activity of TMZ in glioma cell lines." (PMID 37749600, 2023). "Reduced expression levels of ABCA1 (siABCA1-1 and siABCA1-2) in TMZ-resistant glioma cells U118-R and T98G-R were detected by Western blotting, which indicated that ABCA1 expression successfully suffered from interference and knockdown." (PMID 37749600, 2023). "Stem cell transcription factors (SOX2, OCT4, and NANOG) and ABCA1 are responsive to regulation by CEBPD, which directly binds to the promoter regions of those genes in glioma spheroid cells and TMZ-treated glioma cells." (PMID 33436575, 2021).